ENSG00000300966 (novel transcript, antisense to CCDC170)
Synonyms: LOC107986528
Gene: Long non-coding RNA gene on chromosome 6 (151,610,427 to 151,616,868, reverse strand). Ensembl gene ENSG00000300966.
Gene Ontology:
Molecular function: U4 snRNA binding
Biological process: formation of quadruple SL/U4/U5/U6 snRNP; spliceosomal tri-snRNP complex assembly
Cellular component: U4/U6 x U5 tri-snRNP complex; U6 snRNP